AQP4 (aquaporin 4)
Diseases named in the same sentence as AQP4 in open-access papers (continued):
Sharing a sentence is not in itself a finding about the gene and the disease.
Stroke (continued). "In patients with malignant (large) strokes, imaging studies show edema spreading in peri-infarct white matter where astrocytic AQP4 is abundantly expressed, implicating AQP4 in the rapid water uptake that can cause life-threatening brain herniation." (PMID 40943104, 2025). "Another study looking at AQP4 expression in grey and white matter of autopsied human stroke brain and controls found that AQP4 expression and lobe differ markedly between brain regions after ischemia." (PMID 40943104, 2025). "Herein, we analyzed the coverage of the vasculature by astrocyte endfeet by immunolabeling aquaporin 4 (AQP4), and its association with CD31+ microvessels at the injury site 4 days after stroke." (PMID 40277075, 2025). "Beyond studies directly demonstrating that TMS enhances AQP4 polarization to improve glymphatic function in AD models, additional evidence from murine stroke models suggests that TMS can also induce astrocytes to shift from an A1 to an A2 phenotype." (PMID 40746364, 2025). "Agents like TGN-020 and new-generation AQP4 inhibitors should continue to be explored in preclinical stroke models, with attention to dosing windows and combination with reperfusion therapies." (PMID 40943104, 2025). "The search terms used were (“Aquaporin-4” OR “AQP4”) AND (“stroke” OR “brain infarct” OR “cerebrovascular disease” OR “cerebrovascular accident”) AND (“edema” OR “oedema” OR “brain edema” OR “brain swelling” OR “water homeostasis”)." (PMID 40943104, 2025). "Certainly, future research endeavors should aim to disentangle the signaling mechanisms that govern AQP4’s expression and localization during stroke." (PMID 40943104, 2025). "This apparent contradiction can be explained by the dual and time‐dependent role of AQP4 in stroke pathophysiology." (PMID 39927473, 2025). "While NMO is distinct from stroke, it demonstrates that losing AQP4 is harmful in the context of inflammation and vasogenic edema, aligning with the notion that AQP4 is protective for edema resolution." (PMID 40943104, 2025). "Inhibiting p38 MAPK attenuates the post-ischemic rise in AQP4 and can reduce astrocyte swelling and cell death, suggesting this pathway upregulates AQP4 during stroke-induced stress." (PMID 40943104, 2025). "Dexamethasone can downregulate AQP4 expression (helpful in vasogenic edema from brain tumors), but steroids have broad effects and their efficacy in stroke edema is unproven." (PMID 40943104, 2025). "These efforts require interdisciplinary collaboration between neurologists, radiologists, molecular biologists, and translational scientists to ensure that modulation of AQP4 becomes a viable component of personalized stroke therapy." (PMID 40943104, 2025). "These regional differences suggest that AQP4 abundance and distribution critically shape the extent of cytotoxic edema following stroke." (PMID 40943104, 2025). "Dysfunction of the glymphatic system, probably related to disrupted AQP4 expression, has been observed in animal models of AD and stroke." (PMID 40988734, 2025). "Further research is needed to establish standardized AQP4 detection methods and define clinically relevant cutoff values for stroke diagnosis and prognosis." (PMID 40142325, 2025). "The identification of AQP4 modulators and inhibitors offers promising new therapeutic possibilities, with the potential to more effectively reduce stroke-related morbidity and mortality." (PMID 40142325, 2025). "Yet, given the huge unmet need in managing stroke edema, where current treatments are crude and often insufficient, pursuing AQP4-based therapies remains a promising and rational strategy that should be further and seriously explored." (PMID 40943104, 2025). "This paradoxical “friend or foe” behavior of AQP4 in stroke pathology is the central focus of our review." (PMID 40943104, 2025). "This illustrates how ubiquitin-mediated protein turnover can acutely change AQP4’s membrane presence during stroke." (PMID 40943104, 2025).
Stroke (continued). "Beyond stroke, other CNS injury models show similar patterns of AQP4 function and involvement in brain edema." (PMID 40943104, 2025). "In the present study, we found significant upregulation of AQP4 expression, mainly located in the striatum and cortex of stroke control rats compared to the healthy control." (PMID 40360812, 2025). "Immunolabelling of HSP70 corroborated the upregulation of HSP70 found in immunoblotting, with increased HSP70 immunoreactivity in AQP4-positive endfeet after stroke." (PMID 39796165, 2025). "We will also discuss translational insights and therapeutic attempts to modulate AQP4, highlighting both the challenges and opportunities in targeting this protein for stroke and edema treatment." (PMID 40943104, 2025). "AQP4 knock-out mice and wildtype mice treated with AQP4 inhibitors have been demonstrated to be protected from oedema after stroke." (PMID 40533800, 2025). "Addressing these limitations will be essential for the successful translation of AQP4-targeted strategies into effective, personalized treatments for stroke-related brain edema." (PMID 40943104, 2025). "Much of our understanding of AQP4’s roles comes from controlled animal studies, which have looked at AQP4 function in various stroke and brain injury models; these studies consistently support a phase-dependent dual role for AQP4." (PMID 40943104, 2025). "Using a middle cerebral artery occlusion (MCAO) mouse model, we assessed AQP4's role in post‐stroke inflammation." (PMID 39444081, 2024). "Consistent with prior studies, acute AQP4 inhibition using TGN-020 decreased infarct volume 2 days post-stroke and reduced peri-infarct AQP4 polarization." (PMID 37695472, 2024). "We also detected bands between 100 and 150 kDa MW, suggesting the possible presence of AQP4 tetramers in EV cargo during stroke." (PMID 39596535, 2024). "Several approaches have been proposed to inhibit AQP4 mislocalisation as a treatment for central nervous system (CNS) injury and stroke, with the aim of stabilising the BBB and disrupting the blood-spinal cord barrier disruption." (PMID 38472255, 2024). "Pathohistological studies on post-mortem human samples revealed an upregulation of AQP4 in the glial scar during the chronic stages after stroke." (PMID 39596535, 2024). "Elevated blood pressure post-stroke enhances oxidative stress and AQP4-mediated BBB permeability, exacerbating edema and early neurological deterioration." (PMID 39768394, 2024). "Evidence on the participation of astrocytic AQP-4 water channels in different movement disorders and their pathophysiology, such as stroke and PD, further supports the role of this channel in motor function." (PMID 39534317, 2024). "Post-stroke acute inhibition of aquaporin 4 (AQP4) is known to exacerbate inflammation and apoptosis, yet the underlying mechanisms are not fully understood." (PMID 37695472, 2024). "They effectively showcased that targeting AQP4 leads to a substantial reduction in cerebral edema during the initial acute phase of stroke, using a photothrombotic stroke model." (PMID 38336645, 2024). "When the blots were probed with the anti-AQP4 antibody, a prominent band in TEVs and a discrete one in ADEVs at around 37 kilodaltons (kDa) were detected in all post-stroke samples obtained at D1, D7, and M1 after injury." (PMID 39596535, 2024). "Studies using AQP4‐null mice demonstrated a protective effect of AQP4 deletion during the acute phase of stroke or TBI." (PMID 37702572, 2024). "In a rat pup stroke model, the induction of AQP4 in the border regions limited the edema formation that occurs later after injury (24–72 h), thus preserving the tissue." (PMID 39596535, 2024). "Animal model studies suggest that AQP-4 plays pathological responses in AD, Parkinson’s, traumatic brain injury, and stroke." (PMID 39201439, 2024).
Stroke (continued). "As the horizon of stroke research expands, delving deeper into the multifaceted roles of proteins like AQP4 will undoubtedly pave the way for innovative treatments." (PMID 39444081, 2024). "In the present study, we investigated the role of AQP4, a key protein in the maintenance of brain water homeostasis, and its potential impact on post‐stroke neuroinflammation and neuronal apoptosis." (PMID 39444081, 2024). "SNPs in the AQP4 gene, such as rs9951307 (stroke) and rs1058427 (ICH), correlate with severe edema and poor outcomes, highlighting a genetic basis for edema vulnerability." (PMID 39768394, 2024). "There is no effective drug targeting AQP4 that has been directly approved for clinical use, although AQP4 has been proven to have therapeutic potential in stroke, traumatic brain injury, and other neurodegenerative diseases." (PMID 36769234, 2023). "The decrease of periinfarct astrogliosis and AQP4 depolarization promotes poststroke brain damage, indicating a possible beneficial therapeutic approach after stroke to improve the restoration of neurological function." (PMID 37554272, 2023). "The abnormal expression of AQP4 is also involved in the dysfunction of the lymphatic pathway in animal models of traumatic brain injury, AD and stroke." (PMID 37238624, 2023). "Astrocyte swelling and astrogliosis along with mislocalization of perivascular astrocytic AQP4 as well as glymphatic impairment were also revealed in stroke." (PMID 37048052, 2023). "By administering TFP to photothrombotic stroke mouse models, researchers confirmed that AQP4 mRNA and protein expression levels in the brain decreased, accompanied by significantly reduced cerebral edema." (PMID 37464832, 2023). "Among these, AQP4 has been the focal point of numerous studies, especially in relation to various brain conditions, spanning acute afflictions such as stroke and traumatic brain injury to chronic autoimmune neurodegenerative ailments." (PMID 37762642, 2023). "Astrocytic AQP4 also has a complex bimodal function in stroke pathology: knockdown or inhibition of AQP4 in astrocytes can mediate protective effects or cause damage." (PMID 37435045, 2023). "In the later phases post-stroke, the upregulation of AQP4 expression aids in the leaking of plasma proteins and water into the interstitial space of the brain by disrupting the BBB integrity, exacerbating vasogenic edema." (PMID 38178909, 2023). "Longitudinal changes in AQP4 expression have also been noted; its expression remains elevated up to 28 days in the perilesional area following stroke and SCI." (PMID 37762642, 2023). "Specifically, AQP4 expression typically escalates 48 h post-insult in models of stroke, TBI, and neuroinflammatory lesions." (PMID 37762642, 2023). "Specifically, in ischemic models involving transient middle cerebral artery occlusion, AQP4 is acutely up-regulated in the astrocyte endfeet adjoining blood vessels, reaching peak levels approximately 1 h post-stroke onset." (PMID 37762642, 2023). "In contrast, AQP4 promotes the elimination of angiogenic cerebral edema in the late stage of stroke." (PMID 37091130, 2023). "Administration of an aquaporin 4 inhibitor also resulted in less brain swelling and apoptosis 3 and 7 days after stroke." (PMID 37767530, 2023). "Given the dual role of AQP4 in both the formation and resolution of post-stroke edema, therapeutic strategies targeting AQP4 need to be carefully timed and executed." (PMID 38178909, 2023). "Thereby, AQP4, located at the astrocyte’s end-feet, was discussed to have a pivotal role in edema formation after stroke." (PMID 35682557, 2022). "Studies revealed that acute inhibition of AQP4 after stroke diminishes brain edema, however, its effect on peri-infarct astrocyte reactivity and the subacute outcome is unclear." (PMID 35592320, 2022).
Stroke (continued). "Up to date, only a few biomarkers, such as ADAMTS13 activity, Aquaporin-4, leukocyte count, and neutrophil to lymphocyte ratio, were found to be associated with post-thrombolytic ENI in stroke." (PMID 36315566, 2022). "AQP4 plays an extensive role in the formation and regression of edema after stroke, the BBB, and the protection of neurons." (PMID 35111362, 2022). "As an important part of the glymphatic system, the AQP4 has been shown to change the location from the end feet of perivascular astrocytes to other places after stroke." (PMID 36278004, 2022). "As a result, the assessment of circulating AQP-4 levels during the acute phase of stroke seems to be able to facilitate stroke prognosis and subsequently optimize patients’ clinical management and final neurological outcomes." (PMID 36278689, 2022). "Stroke (including ischemic stroke and hemorrhagic stroke) is still considered the core cause of VCI, and many in-depth studies have examined the role of AQP4 in stroke." (PMID 35111362, 2022). "Here, we demonstrate that AQP4 is radically reorganized in the infarct border zone one week after experimental stroke." (PMID 35163040, 2022). "Here, we addressed the roles of AQP4 in incipient scar formation using experimental stroke as a model." (PMID 35163040, 2022). "Traditionally, it is thought that post-stroke edema comprises cytotoxic edema and vasogenic edema, in which AQP4 plays inductive and counteractive roles, respectively, with edematous fluid mainly coming from blood plasma." (PMID 35592320, 2022). "AQP4 plays a complex dual role during the cerebral edema process after stroke, aggravating cerebral edema formation in the early stage and reducing edema in the later stage." (PMID 36061592, 2022). "Our results showed that XFZYD alleviated glymphatic dysfunction following stroke by ameliorating AQP4 polarity and anchoring proteins." (PMID 36582539, 2022). "Of these, AQP4, the most abundant aquaporin in the brain, has been reported to involve in brain edema and has potentially important clinical implication by stroke and ischemia research." (PMID 35177771, 2022). "Post-stroke edema, impairment of the blood-brain barrier, as well as upregulation of aquaporin 4 (AQP4) water transport channels, play an essential role in the progression of ischemia and deteriorating disease recovery." (PMID 36425795, 2022). "This study extends the evaluation timepoint of previous studies investigating the effect of TGN-020 on ischemic stroke, providing further supportive evidence that acute inhibition of AQP4 after stroke is a viable therapeutic strategy." (PMID 35592320, 2022). "Contradictory to the finding of the beneficial effect of targeting AQP4 in stroke, another study showed that AQP4 knockout mice had higher mortality and exacerbated neurological impairments, implying that AQP4 contributes to the pathogenesis of stroke." (PMID 35890028, 2022). "AQP4 is also known to provide an influx route for water during the build-up of brain edema following injury or stroke." (PMID 35163040, 2022). "AQP4 is known to be involved in many brain diseases such as stroke and dementia, and AQP4 knockout (AQP4-ko) animals are often used to investigate the function of AQP4." (PMID 36685250, 2022). "Our results showed that acute inhibition of AQP4 by TGN-020 reduced brain edema 1day post-stroke, which is consistent with previous research." (PMID 35592320, 2022). "Overall, the results of the present review are indicative of a link between the circulating levels of BNP, GFAP, RDW, NLR, MMP-9, and AQP4 following stroke and clinical outcome prognostication." (PMID 36278689, 2022). "To further understand the molecular mechanisms of Storax regulating caveolae-mediated transcytosis after stroke, we examined Cav-1, Mfsd2a, AQP4, and PDGFR-β expressions by Western blotting." (PMID 35873558, 2022).
Stroke (continued). "Administration of tPA resulted in further increase of AQP4 in stroke mice, while the tPA-evoked increase was partly prevented by addition of QSYQ at 0.5 g/kg." (PMID 35095486, 2021). "AQP4 has been suggested to play a role in several neurological diseases such as hydrocephalus, stroke and also AD either by an altered gene expression or a change in localisation." (PMID 34838088, 2021). "Increased expression of AQP4 is reported in various disease states, such as stroke and hydrocephalus." (PMID 33897371, 2021). "AQP4 polarization toward the vessel walls was reduced significantly in peri-infarct regions of stroke compared to sham animals (F = 29.46, p < 0.001)." (PMID 33841293, 2021). "In mouse models of transient middle cerebral artery occlusion, the AQP4 expression level in astrocytes was rapidly up-regulated following stroke and correlated with the degree of edema over time." (PMID 34899367, 2021). "AQP4 levels were analyzed in the serum of 60 CAA-related ICH patients and 19 non-stroke subjects by enzyme-linked immunosorbent assay (ELISA)." (PMID 33801197, 2021). "Deferoxamine treatment prevents post-stroke cognitive impairment in diabetes while increasing AQP4 polarity and blood–brain barrier permeability." (PMID 35264947, 2021). "In this section, we review the expression of AQP4 in different subtypes of stroke and then examine the signaling pathways that regulate AQP4 expression and discuss therapeutic opportunities that target AQP4." (PMID 34305569, 2021). "We emphasize the role of the GS in pathophysiology of different stroke subtypes, especially the role of AQP4 in the pathophysiology of stroke." (PMID 34305569, 2021). "Recent experimental studies indicate that the localized inhibition of AQP4 can favor hastened functional recovery in lesions such as stroke or traumatic lesions where inflammatory substrate plays an important role." (PMID 34068922, 2021). "For example, in experimental models of ischaemia or in the deep white matter of post stroke dementia, there is a redistribution of AQP4 from astrocyte end feet to the astrocytic cell bodies." (PMID 32059400, 2020). "Our research team has been studying the role of AQP4 at the early stages of stroke brain tissue damage." (PMID 32138732, 2020). "Several studies of stroke have demonstrated that signal pathways regulate AQP4 expressions, such as the MAPK pathway and NF-κB pathway." (PMID 33192260, 2020). "The coverage of CD31-positive blood vessels by perivascular AQP4 was significantly increased in the perilesion/ipsilateral cortex WT stroke animals compared to sham (WT-Sham compared to WT-Ipsi: 95% CI [−73.27 to −1.223], p = 0.0384)." (PMID 32523952, 2020). "– VEGF and its receptors upregulated persistently. – Increased VEGF increases vessel density and improves stroke outcome.– Beneficial effects of VEGF mediated through aquaporin-4.– Morphology of newly formed vessels resemble that of the developing brain." (PMID 32848875, 2020). "In diseases that alter brain water homeostasis such as brain tumours, stroke and traumatic brain injury, AQP4 expression is increased." (PMID 32059400, 2020). "The work indicates a link between Cav-1, reactive astrocyte morphology and perivascular astrocytic AQP4 expression, brain edema and consequent recovery after stroke." (PMID 32523952, 2020). "An early increase in AQP4 expression occurs 1 h after stroke onset on perivascular end-feet and a late increase on astrocyte processes 48 h after stroke onset." (PMID 32523952, 2020). "Here we used an integrative approach to study possible interaction between AQP4 and caveolin-1 (Cav-1) after stroke." (PMID 32523952, 2020). "In particular, AQP4 is widely involved in water balance in patients with stroke, with increased expression at 6 h after cerebral infarction and a peak at 3 days." (PMID 33613264, 2020).